ZNF506 (zinc finger protein 506)
Description:
May be involved in transcriptional regulation.
Synonyms: DKFZp761G1812
Tractability: PROTAC: ubiquitination databases record sites on it.
Gene: Protein-coding gene on chromosome 19 (19,761,038 to 19,821,751, reverse strand). Ensembl gene ENSG00000081665.
Subcellular location: Nucleus
Pathways (Reactome):
Gene expression (Transcription): Generic Transcription Pathway
Gene Ontology:
Molecular function: DNA-binding transcription factor activity, RNA polymerase II-specific; RNA polymerase II cis-regulatory region sequence-specific DNA binding
Biological process: regulation of DNA-templated transcription; regulation of transcription by RNA polymerase II
Cellular component: nucleolus; nucleus
Genetic constraint (gnomAD): Loss-of-function variants: 8 observed, 11.81 expected, observed/expected ratio (o/e) 0.68, 90% interval 0.4 to 1.22. The upper end of that interval is the gene's LOEUF score, 1.22, which puts it in group 5 of 6, group 1 being the genes least tolerant of losing a copy. Missense variants: 418 observed, 527.04 expected, observed/expected ratio (o/e) 0.79, 90% interval 0.73 to 0.86. Synonymous variants: 153 observed, 173.44 expected, observed/expected ratio (o/e) 0.88, 90% interval 0.77 to 1.01.
Homologues: Orthologues: chimpanzee ZNF506 (98% identical), macaque ZNF506 (96% identical). Paralogues in human: ZNF486 (75% identical), ZNF90 (70% identical), ZNF85 (69% identical), ZNF93 (67% identical), ZNF708 (67% identical), ZNF724 (66% identical), ZNF681 (66% identical), ZNF726 (66% identical), ZNF254 (65% identical), ZNF429 (65% identical), ZNF43 (65% identical), ZNF728 (64% identical), and 164 more.
Diseases named in the same sentence as ZNF506 in open-access papers:
ZNF506 is named in the same sentence as 17 diseases in open-access papers, as found by Europe PMC text mining. Sharing a sentence is not in itself a finding about the gene and the disease. The quoted sentences say what the papers report.
leukemia (2 papers, 2018 to 2023). A malignant (clonal) hematologic disorder, involving hematopoietic stem cells and characterized by the presence of primitive or atypical myeloid or lymphoid cells in the bone marrow and the blood. "Since ZNF506 is aberrant in leukemia, we wanted to assess the role of ZNF506 in class switch recombination." (PMID 30013081, 2018). "Additionally, our study provides insights into the potential role of ZNF506 in leukemia, contributing to the expanding knowledge of KZFPs' crucial function in disease and genome stability." (PMID 37697430, 2023). "Furthermore, we discuss the potential role of KZFPs, particularly ZNF506, in leukemia, where their aberrant expression may influence disease progression." (PMID 37697430, 2023).
lung carcinoma (2 papers, 2018 to 2022). "The low ZNF506 mRNA levels in breast and lung cancers correlated with lower survival probability and worse prognosis." (PMID 36293264, 2022). "Consistently, the ZNF506 gene is frequently dysregulated in various cancers including lung and breast cancers, where low ZNF506 mRNA levels in breast and lung cancers correlated with lower survival probability and worse prognosis 38,39." (PMID 30013081, 2018). "As such, ZNF506 expression levels may have prognostic significance in malignancies including breast and lung cancers." (PMID 30013081, 2018).
acute myeloid leukemia (1 paper, 2023). Acute myeloid leukemia (AML) is a group of neoplasms arising from precursor cells committed to the myeloid cell-line differentiation. "Our study highlights the role of the species-specific gene ZNF506 in binding and repressing the ERVP subfamily, showcasing the potential significance of their interplay in the context of acute myeloid leukemia (AML)." (PMID 37697430, 2023).
breast carcinoma (1 paper, 2018). "However, a search of publicly available databases suggests that high expression of ZNF506 portends superior survival in lung and breast cancers." (PMID 30013081, 2018).
HTLV infection (1 paper, 2023). "Interestingly, previous studies on T-cell leukemia have revealed that ZNF506 expression is significantly suppressed in ATLL cases caused by HTLV-1 infection, compared with T-cell leukemia arising from non-HTLV infection." (PMID 37697430, 2023).
thymoma (1 paper, 2023). A neoplasm arising from the epithelial cells of the thymus. "Utilizing the GEPIA, we observed aberrant expression of ZNF506 in various cancers, such as thymoma and uterine carcinosarcoma." (PMID 37697430, 2023).
viral infection (1 paper, 2023). "Our results revealed that ZNF506 KO NB4 cells were more susceptible to viral infection compared with WT NB4 cells." (PMID 37697430, 2023). "As ZNF506 can potently repress the infectivity of PBS-Pro-utilizing viruses, we next tested which step of viral infection ZNF506 affected." (PMID 37697430, 2023). "We also performed viral infection experiments in 293T cells transfected with GFP-fused KZFPs, including the PBS-Pro-binding human ZNF506 and mouse ZFP809 proteins, and the PBS-Lys-binding human ZNF417 and mouse ZFP961 proteins." (PMID 37697430, 2023).
cancer (3 papers, 2018 to 2023). A tumor composed of atypical neoplastic, often pleomorphic cells that invade other tissues. "In our study, we identified cancer-derived ZNF506 mutations to be defective in recruitment of DNA repair proteins and confer sensitivity to DNA-damaging agents." (PMID 30013081, 2018). "Search of cancer databases such as the TCGA supports a vital role of ZNF506 in tumor suppression and maintenance of genomic stability." (PMID 30013081, 2018). "Cells lacking ZNF506 or harboring mutations found in cancer patient samples are more sensitive to radiation, offering a potential new therapeutic option for cancers with mutations in this pathway." (PMID 30013081, 2018). "Conversely, cells lacking ZNF506 or harboring mutations found in patient samples are more sensitive to radiation and DNA-damaging agents, offering a potential new therapeutic option for cancers with mutations in this pathway." (PMID 30013081, 2018).
infection (1 paper, 2023). The state of being infected such as from the introduction of a foreign agent such as serum, vaccine, antigenic substance or organism. "FACS analysis determining the ratios of RFP+ cells in GFP+ cells revealed that ZNF506 overexpression significantly reduced pMX-RFP pseudoviral infectivity, compared with WT cells or control cells overexpressing ZNF417, but showed much less repression of pBABE-RFP pseudoviral infection." (PMID 37697430, 2023).
ZNF506 also shares sentences with these, for which no sentence is quoted: mental illness (1 paper); neurodegenerative disease (1); oral cancer (1); periodontitis (1); prostate carcinoma (1); T-cell leukemia (1); tumor (1); uterine carcinosarcoma (1).